ZC3HAV1 (zinc finger CCCH-type containing, antiviral 1)
Diseases named in the same sentence as ZC3HAV1 in open-access papers (continued):
Sharing a sentence is not in itself a finding about the gene and the disease.
infection (continued). "Except for DCP1A and ZAP (ZC3HAV1), most ISGs in the YC-2020 group showed a significantly lower expression than the JXA1 group, and gaps widened with the continuance of infection, which imply that YC-2020 may possess a more powerful capacity to weaken the host’s antiviral responses." (PMID 36338035, 2022). "However, ALV-J late infection exhibited no statistical differences in ISG12-1 and ZC3HAV1 mRNA expression in the tumorigenesis phase (p > 0.05)." (PMID 27252695, 2016).
tumor (19 papers, 2012 to 2025). "After that, We investigated the difference in transcriptional expression of VAV1, RHOA, and ZC3HAV1 between tumor samples and adjacent normal liver tissues in various HCC datasets from TCGA, ICGC, and GEO14520." (PMID 36224658, 2022). "The 5 genes (TTC39C, HSPBP1, MAZ, ANK3 and ZC3HAV1) where model AS events occurred were analyzed for the differential expression level between normal breast tissue and tumor tissue." (PMID 35988113, 2022). "It was indicated that VAV1 expression was higher in normal tissues than in tumor samples, whereas, the elevated expression of RHOA and ZC3HAV1 was observed in the tumor group." (PMID 36224658, 2022). "Results showed that the expression of ZC3HAV1 is significantly positive correlation of larger tumor diameter (P= 0.028) together with lymph node metastasis (P = 0.03)." (PMID 34319912, 2021). "Except for three RBPs (SNRNP48, DDX6, and ZC3HAV1) out of the 63, the high-expression tumor group had worse clinical outcome for RBPs that were upregulated in IR-1." (PMID 33311498, 2020). "Systemic treatment with decorin resulted in an induction of Peg3 as well as Bmp2k and Zc3hav1 within the tumor stroma as visualized via immunofluorescence and quantified using three-dimensional surface plots of the fluorescent signal." (PMID 23029096, 2012). "Analysis of these stromal genes in context of the co-culture via qPCR revealed a recapitulation of the expression patterns of Peg3, Bmp2k, and Zc3hav1 (P<0.001), the same stromal genes verified as induced by decorin within the tumor xenografts." (PMID 23029096, 2012). "Thus, these in vivo data provides further proof that decorin significantly affects the tumor microenvironment via induction of Peg3, Bmp2k and Zc3hav1 at the protein and transcriptional levels as suggested by the mixed microarray data." (PMID 23029096, 2012). "Interestingly, the tumor-suppressive effects of ZC3HAV1 are dictated by the tumor microenvironment." (PMID 37373394, 2023). "Finally, we constructed a model using four genes, RBMS1, ZC3HAV1, QKI, and RBM38, to calculate the Tumor Immune Dysfunction and Exclusion (TIDE) score." (PMID 37628671, 2023). "Nonetheless, the expression of VAV1, RHOA, and ZC3HAV1 in the tumor group was all up-regulated than that in the normal group in several HCC cohorts from Oncomine database." (PMID 36224658, 2022).
cancer (15 papers, 2017 to 2026). A tumor composed of atypical neoplastic, often pleomorphic cells that invade other tissues. "The result demonstrated a significant value of VAV1, RHOA, and ZC3HAV1 in predicting the therapeutic efficacy of ICIs for patients with various cancer types." (PMID 36224658, 2022). "Among these 10 RBPs, ZC3HAV1 is an antiviral protein, recent studies have shown that it is related to the occurrence of a variety of cancers." (PMID 34926575, 2021). "Although these findings derive from another cancer type, both cell cycle control and KRAS signalling are dysregulated in MM, making ZC3HAV1 a promising gene for further investigation in this context." (PMID 41596441, 2026). "After examining the pulled‐down proteins by lncRNA ARHGAP5‐AS1 using mass spectrometry proteomics, we identified multiple cancer‐related proteins including CSDE1, ZC3HAV1, CCT8, CKAP4, PARP1, PEG10 and APEX1 in HepG2." (PMID 36354136, 2022). "The results showed differential expression levels of ZC3HAV1 between cancer and non-cancer samples, specifically, significantly higher expression in HCC samples compared to healthy samples." (PMID 39513103, 2024). "However, few studies have evaluated the function of ZC3HAV1 in cancer, and no study has focused on the clinical meaning and effect of ZC3HAV1 in PC." (PMID 34319912, 2021).
ZC3HAV1 also shares sentences with these, for which no sentence is quoted: rectal cancer (2 papers); rectal tumor (2); bacterial infection (1); bladder cancer (1); Ebola (1); hepatocellular carcinoma (1); leukemia (1); lymphoma (1); rectal adenocarcinoma (1); schizophrenia (1); thyroid cancer (1).